FANCE (FA complementation group E)
Diseases named in the same sentence as FANCE in open-access papers (continued):
Sharing a sentence is not in itself a finding about the gene and the disease.
tumor (12 papers, 2017 to 2025). "The patient with germline BRCA2 and FANCE pathogenic variants had a loss of expression of both BRCA2 and FANCE in the tumor, suggesting loss of BRCA2 and FANCE function." (PMID 40072012, 2025). "The patient with germline BRCA2 and FANCE pathogenic variants had RNA sequencing data that indicated the homozygous loss of BRCA2 and FANCE in the tumor." (PMID 40072012, 2025). "RNA sequencing suggested a complete loss of expression of HR genes BRCA2 and FANCE in the tumor of a second patient." (PMID 40072012, 2025). "When the mutational signature analysis was updated using COSMIC v325, the tumor with an elevated signature 3 had 2 deleterious germline variants in the HR pathway (BRCA2/FANCE)." (PMID 40072012, 2025). "The correlation analysis between the expression of FANCE protein and clinicopathological characteristics revealed decreased expression of FANCE was associated with older age (p=0.021) and high tumor grade (p=0.035)." (PMID 37779877, 2023). "Correlation analysis of clinical parameters showed that decreased FANCE expression was associated with older age (p=0.021) and higher tumor grade (p=0.035)." (PMID 37779877, 2023). "Multiple anti-tumor-associated biological processes such as cell cycle, DNA repair and apoptotic signaling pathways, and so on, were enriched in response to increased FANCE." (PMID 33592580, 2021). "However, 2 patients with both BRCA2 and either FANCD2 or FANCE germline deleterious variants also had complex genomic tumor profiles with numerous copy number gains, losses, and copy-neutral LOH (CN-LOH) events." (PMID 40072012, 2025). "High FANCE tumors frequently demonstrate resistance to ICIs, ongoing research on its role in the tumor microenvironment and treatment resistance." (PMID 41181115, 2025). "While essential for interstrand cross-link repair, aberrant FANCE expression promotes tumor progression and immune evasion through cell cycle dysregulation." (PMID 41181115, 2025). "This study illustrates the role of FANCE in tumor development and provides a theoretical basis for more precise treatment in the future." (PMID 36685883, 2022). "We further evaluated FANCE expression in different cells of the tumor microenvironment using single-cell RNA sequencing data from the GEO database." (PMID 36685883, 2022). "FANCE’s role in tumor immunity appears to be achieved by altering the function of cancer cells in these cancers." (PMID 36685883, 2022). "First, we examined FANCE expression with prognosis, tumor immunity infiltration, and immunotherapy using bioinformatics methods." (PMID 36685883, 2022). "These indicated that high FANCE expression correlates with less stromal and immune cell infiltration, leading to high tumor purity in the vast majority of tumors." (PMID 36685883, 2022). "We further checked the gene expression in primary tumor versus normal tissue for genes JAK2, PRDM16, LRP1B, NIN, and NKX2-1 with variants repeatedly enriched in variant-based analysis, and, FANCE, enriched in gene-based burden testing, using the TCGA database." (PMID 35954343, 2022). "Immunohistochemical staining of HNSC tissue specimens and adjacent normal tissues revealed that FANCE was strongly stained in tumor tissues, but the staining intensity was lower in adjacent normal tissues." (PMID 33592580, 2021). "We found that the level of FANCE expression correlated with high levels of immune infiltration in four types of immune cells in the TIMER dataset as well as tumor purity." (PMID 33592580, 2021). "The expression of FANCE is inversely proportional to the infiltration of CD4 + T cells and their subsets, tumor-associated macrophages (TAMs), M2 macrophages, but positively co-expressed with M1 macrophages." (PMID 33592580, 2021). "Our results provide insight into the potential function of FANCE in tumor immunology and its potential as a biomarker for cancer." (PMID 33592580, 2021). "Overall, FANCE overexpression inhibited EC tumor growth in vivo." (PMID 37779877, 2023).
tumor (continued). "The results suggest that low expression of FANCE is tumor heterogeneity." (PMID 37779877, 2023). "All 21 tumor cell lines from the CCLE database expressed FANCE." (PMID 36685883, 2022). "In summary, FANCE was identified as the hub gene from the macrophage marker gene set, and it may improve the prognosis of HNSC patients by inhibiting lymphocytes and tumor-associated macrophages infiltration." (PMID 33592580, 2021). "However, in different tumor types, FANCE showed completely opposite effects on prognosis, which suggests the intricate biological mechanism of the FA pathway." (PMID 33592580, 2021). "FANCE is also carried on this chromosome and as a DNA damage response gene act to limit number of point mutations and copy number changes observed in virus-positive MCC, hindering tumor evolution." (PMID 32188490, 2020). "It remains unclear what role of FANCE plays in tumor immunity." (PMID 36685883, 2022). "FANCE expression was analyzed with prognosis, function enrichment, tumor microenvironment (TME), tumor-infiltrating immune cells (TIICs), immune-regulated genes, immune checkpoint genes, microsatellite instability (MSI), TMB, and neoantigens." (PMID 36685883, 2022). "We further analyzed FANCE expression and MSI, TMB, and neoantigens to predict the tumor immunotherapy responses." (PMID 36685883, 2022). "We analyzed FANCE expression and TME, TIICs, immune-regulated genes, and immune checkpoint genes to investigate tumor immunity." (PMID 36685883, 2022). "Further research is needed to explore the role of FANCE in HNSC cells and its molecular mechanism that affects different phenotypes of macrophages in tumor microenvironment." (PMID 33592580, 2021).
cancer (11 papers, 2015 to 2023). A tumor composed of atypical neoplastic, often pleomorphic cells that invade other tissues. "FANCE expression was positively associated with MSI in seven cancers including UCEC, UCS, STAD, BRCA, BLCA, LUSC, SARC, and negatively in DLBC, TGCT." (PMID 36685883, 2022). "Our results suggest that immune cell infiltration levels were associated with FANCE expression in most cancers." (PMID 36685883, 2022). "In this study, the overexpression of FANCE is associated with the improved prognosis of a variety of cancers, which is consistent with the results of previous studies and is due to the same biological mechanism." (PMID 33592580, 2021). "Our results suggest that FANCE has clinical associations with a variety of cancers." (PMID 36685883, 2022). "Mutations in FANCE cause damage to the FA pathway, thereby increasing cancer susceptibility." (PMID 33592580, 2021). "We performed a pan-cancer analysis of FANCE expression with the prognostic and immunological role in 33 different cancers based on information extracted from databases." (PMID 36685883, 2022). "Results showed MHC genes, including TAPBP, TAP1, and TAP2, were highly positively correlated with FANCE in most cancers." (PMID 36685883, 2022). "The results indicated that FANCE contributes to regulating the immune checkpoint inhibitor (ICI) therapy response in these cancers." (PMID 36685883, 2022). "High expression of FANCE affected shorter overall survival (OS) in seven cancers and longer overall survival in three cancers." (PMID 36685883, 2022). "Our results suggest that FANCE is correlated with clinical prognosis, immune infiltration, and immunotherapy in a variety of cancers." (PMID 36685883, 2022). "As a marker gene for macrophages, FANCE was found to correlate significantly with macrophage infiltration levels in 15 types of cancers from TCGA data." (PMID 33592580, 2021). "FANCE methylation levels in different cancers showed the opposite trend, upregulated in KIRP and downregulated in LUSC, while FANCC methylation was upregulated in THCA and downregulated in UCEC." (PMID 34869316, 2021). "In 7 of these cancers, the expression of FANCE was significantly negatively correlated with the infiltration level of CD4 + T cells." (PMID 33592580, 2021). "FANCE expression regulated TIICs infiltration related to cancer prognosis." (PMID 36685883, 2022). "FANCE expression and activity scores were upregulated in 15 and 21 cancers." (PMID 36685883, 2022). "FANCE correlated with immunity infiltration and predicted the response to immunotherapy in cancers." (PMID 36685883, 2022). "In conclusion, this study systematically described the role of FANCE in different cancer types." (PMID 36685883, 2022). "Our findings suggest that FANCE potentially serves as a biomarker for cancer prognosis." (PMID 36685883, 2022). "We aimed to provide a comprehensive understanding of the role of FANCE in cancers." (PMID 36685883, 2022). "Conclusively, FANCE potential to serve as a biomarker for cancer prognosis and may predict cancer immunotherapy responses." (PMID 36685883, 2022). "We investigate the prognostic and immunological effects of FANCE on various cancers." (PMID 36685883, 2022). "We hypothesize FANCE expression enhances the effectiveness of immunotherapy in cancers with positive MSI." (PMID 36685883, 2022). "The results indicated that FANCE regulation of ICI therapy response might be related to cancer prognosis in these cancers." (PMID 36685883, 2022). "However, the mechanism that FANCE contributes to the development and progression of cancer is still unclear." (PMID 36685883, 2022). "In addition, we explored that FANCE functions in cancers by downregulating DNA repair and DNA damage, and upregulating angiogenesis at the single-cell level using the CancerSEA database." (PMID 36685883, 2022). "Relationship between expression of FANCE and immune cell infiltration in various cancers." (PMID 33592580, 2021).
cancer (continued). "Since FANCE was found to be closely related to the infiltration of a variety of cells in the immune microenvironment, we are interested in whether changes in FANCE expression can predict the prognosis of other cancers." (PMID 33592580, 2021). "Relationship between FANCE expression and classic cancer-related pathways / biological processes." (PMID 33592580, 2021). "Finally, the results of pan-cancer analysis showed that the transcriptional expression of FANCE can predict favorable prognosis of various malignancies including HNSC." (PMID 33592580, 2021). "In addition, in six and five of these cancer data, FANCE was significantly negatively correlated with neutrophil and dendritic cell infiltration, respectively." (PMID 33592580, 2021). "The results indicate FANCE may regulate ICI therapy response and inspire new therapies development for these cancers." (PMID 36685883, 2022). "Despite its importance for assembly and functionality of the FA core complex, no pan-cancer analysis of FANCE was performed." (PMID 36685883, 2022). "This hypothesis is supported by the signature of positive selection of some FA/BRCA components (BRCA2, FANCA, FANCE, and FANCL) identified in long-lived and cancer-resistant species." (PMID 30487452, 2018). "Similar to HNSC, FANCE was negative correlated with macrophage infiltration in 15 other cancers, indicating that FANCE has the same immunoregulatory mechanism in a variety of cancers." (PMID 33592580, 2021). "The expression of FANCE and macrophage infiltration in these types of tumors were also significantly negatively correlated, suggesting that FANCE may have the same mechanism as HNSC in pan-cancer." (PMID 33592580, 2021). "Our results show that there is a negative correlation between FANCE and almost all recognized immune cells, and negative correlations have been observed not only in HNSC but also in various cancers." (PMID 33592580, 2021).
FANCE also shares sentences with these, for which no sentence is quoted: anemia (4 papers); colorectal cancer (3); lung adenocarcinoma (2); lung squamous cell carcinoma (2); rectal adenocarcinoma (2); breast tumors (1); butyrylcholinesterase deficiency (1); cervical squamous cell carcinoma (1); colon adenocarcinoma (1); colon cancer (1); Ehlers-Danlos syndrome (1); endocervical adenocarcinoma (1); endometrioid adenocarcinoma (1); familial cancer of the breast (1); Fanconi anemia complementation group E (1); gastrointestinal stromal tumor (1); glioblastoma multiforme (1); glioma (1); Hepatitis B (1); hereditary cancer-predisposing syndrome (1); lymph node metastases (1); oral cancer (1); oropharyngeal cancer (1); pancreatic cancer (1); paraganglioma (1); parasitemia (1); Parkinson ́s disease (1); pheochromocytoma (1); pituitary stalk interruption syndrome (1); pontocerebellar hypoplasia (1).
A further 10 diseases each share a sentence with FANCE in 1 paper.